HKDC1 (hexokinase domain containing 1)
Diseases named in the same sentence as HKDC1 in open-access papers (continued):
Sharing a sentence is not in itself a finding about the gene and the disease.
breast carcinoma (6 papers, 2019 to 2025). "Acknowledging the pivotal role of HKDC1 in cancer progression, we undertook an in vitro study aimed at elucidating its function within gastric and breast cancer cell lines." (PMID 40124623, 2025). "Further, HKDC1 modulates the oxidative stress, apoptosis, proliferation, and metastasis in breast cancer." (PMID 32943998, 2020). "Our results show that HKDC1 expression modulates oxidative stress, apoptosis, and mitochondrial function in breast cancer cells." (PMID 31058090, 2019). "This provides a novel therapeutic strategy through targeting the PGC1β/HKDC1 signaling pathway for breast cancer treatment." (PMID 31058090, 2019). "We also measured the binding abilities of PGC1β, SREBP1 and SREBP2 on the HKDC1 promoter using the ChIP technique in different breast cancer cells." (PMID 31058090, 2019). "This is the first time that the mechanism for PGC1β-mediated HKDC1 expression has been discovered in breast cancers, and this provides a new strategy for cancer therapy through targeting the PGC1β/HKDC1 signaling pathway." (PMID 31058090, 2019). "Overexpression of HKDC1 increases while knockdown of HKDC1 decreases in vitro breast cancer cell proliferation and in vivo tumor growth, metastasis, and mouse survival." (PMID 31058090, 2019). "In this study, we demonstrate that HKDC1 expression is increased significantly in breast cancer cells, and is regulated by PGC1β/SREBP1-mediated co-activation on the HKDC1 promoter." (PMID 31058090, 2019). "Our results show that the expression of both PGC1β and HKDC1 increases in breast cancer cells, and the HKDC1 expression is regulated by PGC1β." (PMID 31058090, 2019). "This provides powerful evidence that the expression of PGC1β and HKDC1 is increased in human breast cancer tissues." (PMID 31058090, 2019). "In this study, we aim to investigate the potential effect and mechanism of HKDC1 on the contribution of breast cancer." (PMID 31058090, 2019). "HKDC1 overexpression significantly promotes cell proliferation in breast cancer cells, whereas HKDC1 knockdown suppressed this effect." (PMID 31058090, 2019). "Furthermore, in breast cancer, HKDC1 governs SREBP1-mediated metabolic programs that support tumor growth and metastatic dissemination." (PMID 41049000, 2025). "HKDC1 is prominently expressed in both breast cancer cells and clinical tumor specimens." (PMID 41049000, 2025). "HKDC1 regulates metastasis, proliferation, apoptosis, and oxidative stress in breast cancer." (PMID 36518326, 2022). "In this study, we show that HKDC1 expression in breast cancer cells is increased significantly." (PMID 31058090, 2019). "Our preliminary data showed that HKDC1 expression is significantly increased in breast cancer cells and clinical tissues, while the mechanism remains unknown." (PMID 31058090, 2019). "We first evaluated the gene expression of PGC1β and HKDC1 in human breast cancer tissues." (PMID 31058090, 2019). "We first evaluated the gene expression of HKDC1 and PGC1β in different breast cancer cells." (PMID 31058090, 2019). "It is the first time that the mechanism behind the role of HKDC1 in tumor development in breast cancer has been identified, leading to the possibility that HKDC1 could be a potential target for cancer therapy." (PMID 31058090, 2019). "Taken together, the HKDC1 expression is increased significantly in breast cancer cells and tumor tissues, and is co-activated by PGC1β through the SREBP1 binding motif on the HKDC1 promoter." (PMID 31058090, 2019). "Our results indicate that HKDC1 is located on the mitochondria membrane, interacts with VDAC1, and modulates the permeability transition pore, subsequently modulating glucose uptake in breast cancer cells." (PMID 31058090, 2019).
pancreatic cancer (6 papers, 2023 to 2025). "The elevated level of HKDC1 in pancreatic cancer is associated with reduced CD8 T cells, which could contribute to the poorer prognosis observed in patients with high HKDC1 expression." (PMID 38434978, 2024). "Research have demonstrated that HKDC1 expression is significantly increased in various cancers, such as gastric, lung, hepatocellular, and pancreatic cancers, which indicating its potential for early identification." (PMID 41049000, 2025). "Patients with elevated levels of HKDC1 exhibited reduced immune scores and stromal scores, indicating that HKDC1 overexpression hampers the infiltration of immune cells in pancreatic cancer, thereby impeding its anti-tumor effects." (PMID 38434978, 2024). "The EDU tests demonstrated that the diminished expression of HKDC1 significantly decreased the proliferative capacity of the pancreatic cancer cells compared to the control group." (PMID 38434978, 2024). "As HKDC1 functions as a hexokinase, our objective was to investigate the impact of HKDC1 on glycolysis in pancreatic cancer cells." (PMID 38434978, 2024). "Following that, we investigated the expression of HKDC1 in pancreatic tumor cells and normal cells using qPCR and WB." (PMID 38434978, 2024). "Western blot analysis showed the high expression level of HKDC1 in several common pancreatic cancer cell lines." (PMID 36834681, 2023). "HKDC1 is identified as a promising biomarker for early cancer diagnosis, with significantly elevated expression across multiple malignancies, including gastric, lung, hepatocellular, and pancreatic cancers, correlating with tumor growth and glycolytic activity." (PMID 41049000, 2025). "imilarly, HKDC1 knockdown hindered cellular proliferation and migration in HCC cells in vitro, while in pancreatic cancer it promotes proliferation, migration, and invasion while inhibiting apoptosis 15,16,26." (PMID 41049000, 2025).
diabetes (5 papers, 2015 to 2024). "The dysregulation of glucose is commonly associated with Type 2 diabetes, and activation of HKDC1 is considered as a potential target for diabetes therapeutics while inhibition of HKDC1 could lead to the undesired inhibition of glucose metabolism." (PMID 25991664, 2015). "Similarly, genes ABCB11 (chromosome 2), ADCY5 (chromosome 3), CDKAL1 (chromosome 6), ANK1 (chromosome 8), GLIS3 (chromosome 9), and HKDC1 (chromosome 10) have been linked to various aspects of diabetes, including insulin release, glucose levels, β-cell function, and insulin resistance." (PMID 38274506, 2023). "Specifically, the HOXC-AS2/miR-876-5p/HKDC1 axis can regulate pyroptosis in endometrial cancer cells, especially in patients with diabetes, and EMT in glioma cells." (PMID 37944249, 2023).
endometrial cancer (4 papers, 2022 to 2025). Primary or metastatic malignant neoplasm involving the endometrium (mucous membrane that lines the endometrial cavity). "In endometrial cancer under hyperglycemic conditions, the miR-876-5p/HKDC1 axis drives cell proliferation and migration, underlying metabolic adaptation in diabetic patients." (PMID 41049000, 2025). "In a glucose-induced tumor microenvironment, the HOXC-AS2/miR-876-5p/HKDC1 axis regulates endometrial cancer progression." (PMID 36467881, 2022). "Furthermore, under hyperglycemic conditions, the HOXC-AS2/miR-876-5p/HKDC1 axis drives endometrial cancer progression, illustrating how HKDC1 interacts with environmental factors to promote tumorigenesis." (PMID 41049000, 2025). "HKDC1 causes pyroptosis and metabolic advantage in lactate‐rich environments by boosting ROS and glycolysis activation, resulting in the creation of acidic TME and favorable inflammatory that leads to endometrial cancer cell proliferation and migration." (PMID 37752941, 2023). "In diabetic endometrial cancer patients, hexokinase domain‐containing 1 (HKDC1) is upregulated." (PMID 37752941, 2023).
lung carcinoma (4 papers, 2018 to 2022). "HKDC1 is a human hexokinase gene that is overexpressed in tumor tissues and is considered to be a promising target for a treatment of lung cancer." (PMID 29420561, 2018). "Previous bioinformatics analysis predicted that HKDC1 could be a promising therapeutic target for lung cancer." (PMID 32943998, 2020). "However, this hypothesis remains to be validated, and the downstream mechanism of HKDC1 in lung cancer needs to be explored." (PMID 32943998, 2020). "However, among the hexokinases only HKDC1 was shown to be dramatically overexpressed in the tumor tissues, which suggested a pivotal role of HKDC1 in cancer and particularly, a potentially promising therapeutic target for lung cancer." (PMID 29420561, 2018). "The upregulated genes included CYP4F3, IL1RL1, PTGS2, and CXCL8, which are related to inflammation; HKDC1, MYEF2 and CYP1A1, which are related to hepatocarcinoma or lung carcinoma; and SLC7A11 and NEFM, which are related to neuronal damage." (PMID 33247188, 2020).
type 2 diabetes (4 papers, 2015 to 2023). "Despite these similarities, a much greater effect size for MTNR1B in GDM compared to type 2 diabetes and association of HKDC1, which encodes a hexokinase, with GDM but not type 2 diabetes suggest some differences in the genetic architecture of GDM." (PMID 37047019, 2023).
colon carcinoma (3 papers, 2018 to 2025). "As the LF-dependent NT5DC3/HKDC1 expression alteration in colon cancer, we sought to determine the relevance of LF and downstream targets NT5DC3/HKDC1 in HT29 tumor model in vivo." (PMID 36855062, 2023). "This study reveals the underlying mechanism by which LF-dependent DNA 5mC and RNA m6A remodeling in epigenetically regulating the NT5DC3/HKDC1 axis, and subsequently inhibiting colon cancer progression under hyperglycemia." (PMID 36855062, 2023). "As verified by RT-qPCR, a dysfunction of mitochondrial respiration chain and ER stress resulted in a partially ATF4-dependent stimulation of KRT16, FAM129A and HKDC1 expression in the HCT116 colon carcinoma cell line." (PMID 29420561, 2018). "Moreover, LF-dependent up-regulating of NT5DC3 and down-regulating of HKDC1 expression provided strong evidence that NT5DC3 and HKDC1 might play pivotal roles in the induction of T2D to colon tumor which could be relieved by LF." (PMID 36855062, 2023). "Through colocalization and immunoprecipitation (IP) experiments, we demonstrated the interaction between HKDC1 and RCOR1 in colon cancer cells." (PMID 40209953, 2025). "Confocal microscopy results also revealed the binding between HKDC1 and RCOR1 in colon cancer cells." (PMID 40209953, 2025). "In brief, we revealed that lactoferrin acts as a suppressor in the progression of colon cancer under a high concentration of glucose, by which epigenetically regulating glucose-dependent DNMT/5mC or WTAP/m6A/NT5DC3/HKDC1 axis." (PMID 36855062, 2023). "Further investigation should be conducted to ascertain whether this mechanism holds true in more clinical T2D-induced colon tumor patients, or whether LF inhibits the progression of the two diseases via acting on WTAP/m6A/NT5DC3/HKDC1 axis in the clinical area." (PMID 36855062, 2023).
lung squamous cell carcinoma (3 papers, 2021 to 2025). "Additionally, HKDC1 serves as a prognostic indicator, with higher levels associated with poor outcomes and overall survival in cancers such as colorectal and lung squamous cell carcinoma, influencing tumor-immune interactions and aiding in personalized therapeutic strategies." (PMID 41049000, 2025). "For example, in lung squamous cell carcinoma, a glycolysis-based three-gene signature inclusive of HKDC1 robustly predicts overall survival 10-12." (PMID 41049000, 2025). "Increased HKDC1 levels have been related to poor outcomes in various cancers, such as colorectal and lung squamous cell carcinoma." (PMID 41049000, 2025). "Additionally, HKDC1 functions as a key regulator of glycolysis and correlates with adverse clinical outcomes in lung squamous cell carcinoma (LUSC)." (PMID 41049000, 2025).
pancreatic adenocarcinoma (3 papers, 2024 to 2025). "In pancreatic adenocarcinoma, the upregulation of HKDC1 is closely associated with cell proliferation, migration, and glycolysis, as well as immune infiltration, further suggesting its critical role in the tumor microenvironment." (PMID 41049000, 2025). "In pancreatic adenocarcinoma, HKDC1 overexpression can suppress anti-tumor immunity by reducing immune cell infiltration, correlating with poorer patient outcomes." (PMID 41049000, 2025). "HKDC1 dysregulation extends to pancreatic adenocarcinoma, where prominent expression enhances proliferation, migration, invasion, and glycolytic flux while suppressing apoptosis and modulating immune infiltration." (PMID 41049000, 2025). "For example, strong correlations between HKDC1 expression and the growth and glycolytic activity of pancreatic adenocarcinoma cells support its role in the identifying early metabolic alterations." (PMID 41049000, 2025).
alcoholic hepatitis (2 papers, 2024 to 2025). Acute hepatitis resulting from ingestion of alcohol. "We note that similar glycolytic re-wiring, particularly HKDC1 up-regulation, has been reported in liver multi-omics studies of alcoholic hepatitis, suggesting a systemic mechanism that spans blood and target organs." (PMID 41009047, 2025).
Alzheimer disease (2 papers, 2014 to 2025). A progressive, neurodegenerative disease characterized by loss of function and death of nerve cells in several areas of the brain leading to loss of cognitive function such as memory and language. "In contrast, HKDC1 levels are reported to decline in aging and Alzheimer’s disease models, where its loss is associated with impaired glucose metabolism, mitochondrial dysfunction, and heightened neuroinflammation." (PMID 41009047, 2025).
Hyperglycemia (2 papers, 2022 to 2023). An increased concentration of glucose in the blood. "A genome-wide association study (GWAS) identified HKDC1 as a risk factor for gestational hyperglycemia." (PMID 35248088, 2022).
Impaired glucose tolerance (2 papers, 2022 to 2023). An abnormal resistance to glucose, i.e., a reduction in the ability to maintain glucose levels in the blood stream within normal limits following oral or intravenous administration of glucose. "HKDC1 is associated with impaired glucose tolerance in old-age pregnant mice whose gene is downregulated by 50%, and is embryonically lethal in HKDC1-KO mice." (PMID 35408874, 2022).
Insulin resistance (2 papers, 2023). Increased resistance towards insulin, that is, diminished effectiveness of insulin in reducing blood glucose levels. "While these associations suggest a role for hepatic Hippo/YAP signaling in insulin resistance, future studies need to explore the causal link between HKDC1 and YAP signaling and whether the changes in whole body glucose homeostasis is dependent or independent of YAP signaling." (PMID 37198225, 2023).
liver disease (2 papers, 2022 to 2023). "This progressive increase in hepatic HKDC1 expression from NASH to LC suggests an association of HKDC1 in the progression of liver disease to LC." (PMID 35902556, 2022). "To do this, we developed a chronic, stable overexpression of hepatic HKDC1 via the use of adeno-associated virus serotype 8 (AAV-8) in adult mice on a low-fat diet to delineate its role in the development of liver disease in the absence of a diet-induced liver disease model." (PMID 37198225, 2023).
retinoblastoma (2 papers, 2025 to 2026). A malignant tumor that originates in the nuclear layer of the retina. "Mechanistically, NSUN2 and YBX1 promoted the malignant behavior and in vitro glycolysis of retinoblastoma through HKDC1, and accelerated tumor growth in vivo." (PMID 41462962, 2025). "In retinoblastoma studies, NSUN2 and YBX1 mediated the m5C modification and mRNA stability of HKDC1, where the global and mRNA m5C levels of retinoblastoma were significantly higher than those of normal retina." (PMID 41462962, 2025). "In retinoblastoma (RB), NSUN2 depletion impairs glycolysis by reducing the stability of HKDC1 mRNA, which is dependent on its m5C modification." (PMID 41522342, 2026).
Anxiety (1 paper, 2026). Intense feelings of nervousness, tension, or panic often arise in response to interpersonal stresses. "We observed age-dependent anxiety, compromised memory and learning, senescence, neuroinflammation, and mitochondrial function deficit in HKDC1-brain knockout mouse models." (PMID 41736382, 2026).
cervical carcinoma (1 paper, 2018). A carcinoma arising from either the exocervical squamous epithelium or the endocervical glandular epithelium. "The similar mode of regulation of KRT16, FAM129A and HKDC1 genes by ER stress and dysfunctional mitochondrial respiration was observed in cervical carcinoma HeLa cells." (PMID 29420561, 2018). "In the cervical carcinoma HeLa cells KRT16, FAM129A and HKDC1 transcripts were also induced in response to treatments associated with ATF4 upregulation and in response to ectopic overexpression of ATF4." (PMID 29420561, 2018).
Cirrhosis (1 paper, 2024). A chronic disorder of the liver in which liver tissue becomes scarred and is partially replaced by regenerative nodules and fibrotic tissue resulting in loss of liver function. "Variants near HKDC1 were mainly associated with cirrhosis, indicating the involvement of potential profibrotic pathways that do not involve the accumulation of hepatic fat." (PMID 38632349, 2024). "Of the 21 ALT variants, 2 were directionally discordant with cirrhosis risk, specifically rs9663238 in HKDC1 and rs79287178 in TNFSF10, whereas all 20 GGT variants had concordant direction of effects with cirrhosis." (PMID 38632349, 2024). "Moreover, we found that the variants near HKDC1, HLA-DQB1 and MAMSTR likely influence cirrhosis via pathways distinct from those related to fatty liver disease." (PMID 38632349, 2024).
cognitive decline (1 paper, 2026). "In this study, we investigated the brain-specific role of the metabolic enzyme hexokinase domain-containing 1 (HKDC1) in neurodegeneration and observed that HKDC1 expression declines in humans with cognitive decline, which matches similar findings in mouse models of AD and aging." (PMID 41736382, 2026).
colorectal adenocarcinoma (1 paper, 2025). The most common type of colorectal carcinoma. "In the context of human CRC, in the TCGA colorectal adenocarcinoma (COAD) cohort, HKDC1 mRNA levels were significantly higher in tumors as compared to normal tissues." (PMID 40391325, 2025).
gestational diabetes mellitus (1 paper, 2022). "Reduced HKDC1 expression is also associated with gestational diabetes mellitus." (PMID 35761325, 2022).
hearing loss (1 paper, 2022). "Compound heterozygous HKDC1 variants were identified as the candidate cause of the sporadic hearing loss in family 1676." (PMID 35248088, 2022).
liver inflammation (1 paper, 2022). "HKDC1 expression was also elevated in human patients with advanced stages of NAFLD, and similar observations were made in mice on a high-fat diet causing high levels of liver inflammation and fibrosis." (PMID 36291085, 2022).
lymph node metastasis (1 paper, 2025). "HKDC1 correlates with lymph node metastasis and advanced TNM stages." (PMID 40977684, 2025).
non-alcoholic fatty liver disease (1 paper, 2022). "Further, since non-alcoholic fatty liver disease (NAFLD) is an independent risk factor for LC, we used a mouse model to explore HKDC1 expression in a NASH-induced LC model (a NASH diet of high fat, cholesterol and sucrose diet (HF-HC-HSD) for 34 weeks)." (PMID 35902556, 2022).
Obesity (1 paper, 2021). Accumulation of substantial excess body fat. "We have also added to the panel rs10762264 in hexokinase domain containing 1 (HKDC1) and rs9939609 in fat mass and obesity-associated protein (FTO)." (PMID 33953693, 2021).